APOA1 (apolipoprotein A1)
Diseases named in the same sentence as APOA1 in open-access papers (continued):
Sharing a sentence is not in itself a finding about the gene and the disease.
ovarian carcinoma (continued). "To investigate the ability of the ApoA1 mimetic peptide to induce the sensitization of ovarian cancer cells to platinum, we exposed SKOV3, OVCAR3, and CAOV3 cells to different concentrations of the peptide and cisplatin, and analyzed cell viability for each condition." (PMID 30745873, 2018). "Moreover, several studies have shown that APOA1 levels can be considered a biomarker with reduced plasma levels in patients with early stage ovarian cancer compared with normal individuals." (PMID 30098223, 2018). "In 2009, the Food and Drug Administration approved the clinical use of OVA-1, a serum test analyzing five biomarkers: CA-125, II-microglobulin (both elevated in ovarian cancer), apolipoprotein A1, prealbumin (transthyretin), and transferrin (which are decreased in ovarian cancer)." (PMID 28448435, 2017). "In addition, we found a significant decrease of APOA1 in serum of ovarian cancer patients as has been shown before in various studies and in tissue." (PMID 25265318, 2014). "Here, we describe several biosensors that developed in the past decade for the detection of ovarian cancer biomarkers such as CA125, human epididymis protein 4 (HE4) and apolipoprotein A1." (PMID 39479573, 2024). "The most recent analysis studied a multiple biomarker combination including APOA1 and APOA2 for ovarian cancer." (PMID 38067270, 2023). "The results showed that the most optimal biomarker combination was a panel of five markers: CA 125, HE4, CA 15-3, APOA1, and APOA2, giving a sensitivity of 93.71% and a specificity of 93.63% for detecting ovarian cancer." (PMID 38067270, 2023). "The combination of transthyretin and apolipoprotein A1 with CA125 improved both the sensitivity and specificity of ovarian cancer diagnosis compared with the sensitivity and specificity of the individual biomarkers determined separately." (PMID 37238197, 2023). "APOA1 and APOA1 mimetic peptides directly reduced the viability and proliferation of ID8 tumor cells and cis-platinum–resistant human ovarian cancer cell lines by the binding and removal of the mitogenic lipid lysophosphatidic acid." (PMID 35577388, 2022). "APOA-1 was lowly expressed in HCC, lung cancer, esophageal cancer, and sarcoma and highly expressed in breast, kidney, and ovarian cancers." (PMID 34790226, 2021). "Currently, ApoA1 is included into FDA-approved OVA1 test, used for ovarian cancer screening and was shown to be decreased in pancreatic cancer." (PMID 32528895, 2020). "The present study showed the significant improvement of sensitivity for the diagnosis of ovarian cancer when using a combination of three serum biomarkers, including CA125, transthyretin, and apolipoprotein A1, using a multiplex liquid assay system." (PMID 22970327, 2012). "The new combination of transthyretin, and apolipoprotein A1 with CA125 improved both the sensitivity and the specificity of ovarian cancer diagnosis compared with those of individual biomarkers." (PMID 22970327, 2012). "In addition, the combination of TTR and APOA1 with MUC16 and TF has shown a 96% overall sensitivity for early detection of ovarian cancer." (PMID 40836974, 2024). "Some epidemiological studies have provided evidence that links the concentration of APOA1, APOB, HDL, LDL, and TG to the risk of OC, but we further analyzed the effect on the subtypes of ovarian cancer to rule out false-positive results." (PMID 36557213, 2022). "The research work reported in the current paper was aimed at disclosing the effects of ApoA1 and an ApoA1 mimetic peptide (Ac-F3,1418A-NH2) on the malignant phenotype of ovarian cancer cells, particularly focusing on cell viability, invasiveness and the potential to synergize with platinum." (PMID 30745873, 2018).
ovarian carcinoma (continued). "Notably, OVA1® is a United States (US) Food and Drug Administration (FDA) approved test, which includes apolipoprotein A-I (APOA1), transthyretin (TTR), transferrin (TF), β2-microglobulin (B2M), along with MUC16, and has demonstrated effectiveness in detecting early-stage ovarian cancer." (PMID 40836974, 2024). "But, the four-biomarker panel (CA125 plus transthyretin plus apolipoprotein A1 plus hemoglobin) did not improve the overall sensitivity and specificity for discriminating between ovarian cancer and healthy individuals (and/or benign group) as compared to the three-biomarker panel in the ROC curve." (PMID 22970327, 2012). "When ApoA1 was combined with CA125 and TTR, not only was a significant improvement observed in the overall sensitivity and specificity, but the panel was also sufficient for maximum discrimination between noncancer, stage I–II and all stages (I–IV) of ovarian cancer." (PMID 33800113, 2021).
hyperlipidemia (55 papers, 2010 to 2026). "In the multivariate analyses in our study, the ApoB/ApoA1 ratio was a stronger risk predictor of IS than hyperlipidaemia, the WHR and HDL-C levels." (PMID 34082746, 2021). "Other gene models at this site were consistent with this result, suggesting that the single nucleotide polymorphism APOA1-75 bp is associated with hyperlipidemia, the A allele being a risk factor for susceptibility to hyperlipidemia." (PMID 33836655, 2021). "The haplotypes of rs501120A-rs1746048T increased and rs501120G-rs1746048C decreased the risk of hyperlipidemia (P < 0.001 for each), showing consistent association with the levels of serum triglyceride, ApoA1 and ApoB." (PMID 31862910, 2019). "Both interventions decreased the oxidative susceptibility of LDL and hepatic APOA1 mRNA expression but only dietary restriction lowered hyperlipidaemia." (PMID 24468233, 2014). "An increase in ApoA-1 is associated with hyperlipidemia and low-density lipiprotein oxidation." (PMID 36293475, 2022). "A comparative study found that carrying the APOA1 -75 A allele could confer a higher risk of hyperlipidemia in obese children." (PMID 24209603, 2013). "Genetic mutation and polymorphism on ApoA-1, ApoE, and LPL is also closely related to hyperlipidemia according to previous research by Baroni, 2003." (PMID 39598239, 2024). "As expected, 3 months of AGBR diet significantly elevated apolipoprotein-A1 levels; however, it reduced apolipoprotein-B levels in patients with hyperlipidemia (p < 0.05)." (PMID 38826585, 2024). "Abnormal or altered expression of ApoA1 and HDL-C can lead to hyperlipidemia, increasing the risk of atherosclerotic and other cardiac complications." (PMID 37351102, 2023). "Meta-analysis of the data indicated that APOA5–1131 T > C, APOA1 -75 bp, APOB XbaI, and APOE gene polymorphisms were significantly associated with hyperlipidemia, with OR values of 1.996, 1.228, 1.444, and 1.710, respectively." (PMID 33836655, 2021). "Of the existing apolipoprotein candidate genes, researchers have correlated APOA1, APOA5, APOB, and APOE gene polymorphisms with hyperlipidemia." (PMID 33836655, 2021). "Meta-analysis of the data indicated that the C allele of APOA5 1131 T > C, the A allele at APOA1-75 bp, the APOB XbaI T allele, and the ε2 and ε4 allele of APOE were each a risk factor for susceptibility for hyperlipidemia." (PMID 33836655, 2021). "However, germinated brown rice consumption significantly increased the apoA1 levels and significantly decreased the apo-B levels, thereby significantly improving hyperlipidemia in the Gbrown group more than that in the R-CK group." (PMID 40869014, 2025). "AGBR relieves hyperlipidemia in patients, as evidenced by reduced levels of triglycerides, total cholesterol, low-density lipoprotein cholesterol, and apolipoprotein-B, and elevated levels of high-density lipoprotein cholesterol and apolipoprotein-A1." (PMID 38826585, 2024). "Notably, dietary intervention with AGBR reduced TG, TC, LDL-c, and apolipoprotein-B levels and elevated HDL-c and apolipoprotein-A1 levels in patients with hyperlipidemia." (PMID 38826585, 2024). "Thus, an association between APOA1 + 83 bp gene polymorphism and susceptibility to hyperlipidemia can be considered not to exist." (PMID 33836655, 2021). "In summary, the results of the present meta-analysis revealed that the C allele of APOA5 1131 T > C, the A allele at APOA1-75 bp, the APOB XbaI T allele, and the ε2 and ε4 alleles of APOE may represent genetic risk factors for susceptibility for hyperlipidemia." (PMID 33836655, 2021). "Therefore, decreased ApoA1 and increased ApoB are the manifestation of hyperlipidemia." (PMID 30231880, 2018). "Compared with the T2D group, the T2D with hyperlipidemia group had significantly higher levels of TG, TC, LDL-C, ApoB/ ApoA1, FBG, HbA1c, hs-CRP, and PCSK9." (PMID 39951410, 2025). "From the aspect of the molecular level, ApoA-1, ApoE, and lipoprotein lipase (LPL) genes are related to hyperlipidemia." (PMID 39598239, 2024).
hyperlipidemia (continued). "This group also had fewer males and smokers, a lower incidence of hyperlipidemia, reduced STEMI occurrences, fewer patients with Killip class ≥ II, and lower levels of LVEF, BMI, DBP, hemoglobin, albumin, triglycerides, ApoA1, and eGFR (P < 0.05)." (PMID 38812817, 2024). "Consistently, in patients with hyperlipidemia, the expression of ANGPTL3, APOA1, TG, and LDL is increased, while PPARα is decreased." (PMID 35755170, 2022). "In the lipid system, the blood chemistry data showed that steroid hormone administration (model group) induced marked hyperlipidemia, such as significantly elevated TG, TC, LDL, ApoA1, and ApoB levels, but significantly decreased HDL levels." (PMID 25759816, 2015). "Administration of 10–22.5 g/kg ABE dose-dependently improved hyperlipidemia by decreasing TG (P <0.01), TC (P <0.01), LDL (P <0.05), ApoA1 (P <0.05), and ApoB (P <0.05) levels, and increasing HDL levels (P <0.05)." (PMID 25471933, 2014). "There were also only one upregulated (heat shock protein family A—Hspa5) and only one downregulated (apolipoprotein A1—Apoa1) hyperlipidaemia-dependent DEPs independent of strain and sex of mice with a similar pattern of changes in 8- and 28-week-old mice." (PMID 40240752, 2025). "Also, the author reviews molecular pathways including the ApoA-1, ApoE, and LPL genes, which are related to hyperlipidemia, to explain the results." (PMID 39598239, 2024). "More interestingly, doses of 20~40 mg/kg TMP could improve hyperlipidemia by decreasing TG, TC, LDL, ApoA1, and ApoB levels and increasing HDL levels." (PMID 25759816, 2015). "The serum apoM concentration in the PNS without hyperlipidemia group also positively correlated with HDL-C, LDL-C, apoA1, and apoB (r = 0.458, P = 0.003; r = 0.423, P = 0.017; r = 0.254, P = 0.022; and r = 0.427, P = 0.036, respectively)." (PMID 28877724, 2017). "While this study did not include subjects with hyperlipidemia or hypertriglyceridemia, both the overweight and lean NAFLD groups showed significantly higher levels of serum LDL, TC, TG, APOB, and lower levels of HDL and APOA1 than their healthy counterparts." (PMID 38034020, 2023).
hepatocellular carcinoma (54 papers, 2009 to 2025). A malignant tumor that arises from hepatocytes. "In hepatocellular carcinoma, the mechanisms underlying the transcriptional repression of apolipoprotein A1 remain obscure." (PMID 38263244, 2024). "Considering the important role ApoA1 played in hepatocellular carcinoma, and chemical inhibition of BDs has been associated with ApoA1 up-regulation, RVX-208 can be used as drugs of hepatocellular carcinoma." (PMID 25849938, 2015). "To test this, we screened a miR library to identify miRs that reduce apoB and increase apoA1 and identified a primate-specific miR, miR-541-3p, that reduces apoB and increases apoA1 secretion in human hepatoma cells." (PMID 39782688, 2025). "We provide evidence that miR-541-3p concurrently reduces apoB and increases apoA1 in human hepatoma cells by regulating 2 different TFs, Casz1 and Znf101." (PMID 39782688, 2025). "Conversely, an increased expression of APOA1 has been seen in other types of cancers, such as small-cell lung carcinoma, hepatocellular carcinoma, and bladder cancer." (PMID 39194522, 2024). "There is further analysis of the diagnostic role of ApoB/ApoA1 ratio in differentiating HCC from LC or CHB and in combination with AFP, a common diagnostic marker for hepatocellular carcinoma." (PMID 38744926, 2024). "It has been discovered that APOA1 can be used to differentiate between individuals who are healthy and those who have liver disease, particularly cirrhosis and hepatocellular carcinoma (HCC)." (PMID 38067270, 2023). "It has previously been shown that curcumin incorporation into stable nanodiscs surrounded by either apolipoprotein ApoA1 or ApoE increases the efficiency of curcumin delivery and apoptosis induction in hepatoma, lymphoma, and glioblastoma cell lines." (PMID 36296810, 2022). "In this study, we investigated the effects of EA on the secretion of two apolipoproteins, apoB and apoA-1, from human HepG2 hepatoma cells." (PMID 34202121, 2021). "Upregulation of ApoA1 gene expression in hepatoma cells in culture, upon exposure to moderate ethanol concentrations in the medium, occurs at the level of RNA and is not dependent on new cholesterol or fatty acid synthesis." (PMID 32563265, 2020). "mRNAs of hepatocyte/hepatoma markers, such as albumin, ApoA1, CYP3A4, and AFP, were detectable in KH and Huh-7.5 cells, but not in A549 cells, indicating that KH cells, similar to Huh-7.5 cells, are derived from hepatocyte/hepatoma cells." (PMID 31138826, 2019). "We examined the mRNA expression levels of several hepatocyte/hepatoma markers, such as albumin, ApoA1, CYP3A4, HNF4α, OATP1B3, and AFP in both cell lines and in lung carcinoma-derived A549 cells by qRT-PCR." (PMID 31138826, 2019). "RVX-208, a derivative of the plant polyphenol resveratrol, binds to BD2 of BRD3 and upregulates ApoA1 which plays an important role in hepatocellular carcinoma." (PMID 30906568, 2019). "Expression of ApoA1 mRNA and protein levels were performed by RT-PCR and Western blot in human hepatoma HepG2 cells and subline HepG2.2.15 cells." (PMID 27015844, 2016). "Similar results had shown the expression of ApoA1 was significantly decreased in hepatoma HepG2.2.15 (integrated the HBV genome) compared to HepG2 cells in vitro." (PMID 27015844, 2016). "In other studies, an inverse correlation between HBV and ApoA1 was found in two hepatoma cell lines and plasma ApoA1 was decreased in chronic hepatitis B patients." (PMID 25115832, 2014). "Znf202 overexpression in mouse hepatoma cells mhAT3F2 resulted in downregulation of members of the Apoe/c1/c2 and Apoa1/c3/a4 gene cluster." (PMID 23469003, 2013). "Apolipoprotein A1 (ApoA1) is known for its role in reverse cholesterol transport and anti-inflammatory activities, and reduced ApoA1 levels have been correlated with the progression and metastasis of hepatocellular carcinoma." (PMID 40612869, 2025).
hepatocellular carcinoma (continued). "In hepatocellular carcinoma, low levels of APOA1 were associated with poorer progression free survival (PFS), thus APOA1 may be a useful predictor of recurrence in hepatocellular carcinoma." (PMID 35421932, 2022). "In these studies, curcumin nanodiscs with ApoA1 scaffold protein showed increased apoptosis in human hepatoma and lymphoma cell lines over curcumin alone controls, and ApoE curcumin nanodiscs demonstrated increased apoptosis and bioavailability in glioblastoma cells." (PMID 36296810, 2022). "In this context, in the present study, we investigated whether EA also affects the secretion of lipoproteins (apoB and apoA-1) from the hepatocytes using a human hepatoma cell line, HepG2." (PMID 34202121, 2021). "Meta-analysis showed that lower APOA1 was associated with unfavorable cancer-specific survival and shorter DFS in overall cancer, inferior total time to recurrence in hepatocellular carcinoma, poorer locoregional RFS, and distant metastasis-free survival in nasopharyngeal carcinoma." (PMID 34211824, 2021). "Furthermore, the luciferase activities of ApoA1 promotor was also down regulated by HBV in hepatoma cells." (PMID 27015844, 2016). "An inverse correlation between HBV and ApoA1 was found in two hepatoma cell lines." (PMID 25115832, 2014). "ApoA1 can suppress hepatocellular carcinoma (HCC) by promoting cell cycle arrest and enhancing tumor cell apoptosis via inactivating the mitogen-activated protein kinase (MAPK) signaling pathway." (PMID 36506554, 2022). "Our study investigated the serum ApoA-1 level for the prognosis of 443 patients with hepatocellular carcinoma (HCC) and its effects on tumor cells." (PMID 27683106, 2016). "Given that JQ1 strongly upregulates ApoA1 in HepG2 cells, it can be used in combination with RVX-208 as a multitarget inhibitor in hepatocellular carcinoma." (PMID 30906568, 2019). "The decrease in apolipoprotein A1 transcription, intracellular and secreted apolipoprotein A1, and circulating HDL levels in hepatocellular carcinoma suggests that this pathway may have a tumor-suppressing function." (PMID 38263244, 2024). "We show that these analogs significantly reduced apolipoprotein B secretion in Huh-7 human hepatoma cells and human primary hepatocytes without affecting apolipoprotein A1 secretion and cellular lipid levels." (PMID 35278429, 2022). "We show that the miR-30c-3p passenger strand can be modified and duplexed with native miR-30c-5p to augment delivery to hepatoma cells and to reduce apoB secretion without affecting apoA1 secretion." (PMID 35278429, 2022). "Moreover, expression of ApoA1 mRNA and protein levels was inhibited by HBV in the dose dependent manner in hepatoma cells." (PMID 27015844, 2016). "HBV mRNAs and ApoA1 mRNA had shown a negative correlation in two hepatoma cell lines." (PMID 27015844, 2016). "No significant changes in secreted levels of APOA1 were observed in either hepatoma cell line." (PMID 23166513, 2012). "The aim of this study was to propose a prognostic scoring system based on preoperative serum apolipoprotein A-1 and C-reactive protein (ApoA-1 and CRP, AC score) levels and to evaluate the prognostic value of these markers in patients with hepatocellular carcinoma (HCC)." (PMID 30486825, 2018).